CD163L1 (CD163 molecule like 1)
Synonyms: CD163b; M160; SCARI2; WC1
Tractability: Antibody: UniProt places it where antibodies can reach, with high confidence; UniProt predicts a signal peptide or a membrane-spanning region; its Gene Ontology location is reachable by antibodies, with medium confidence.
Gene: Protein-coding gene on chromosome 12 (7,346,685 to 7,479,897, reverse strand). Ensembl gene ENSG00000177675.
Subcellular location: Cell membrane (Isoform 1); Cell membrane (Isoform 2); Secreted (Isoform 3)
Subcellular location (Human Protein Atlas): Centrosome; Cytosol; Nucleoplasm
Gene Ontology:
Molecular function: scavenger receptor activity
Biological process: vesicle-mediated transport
Cellular component: external side of plasma membrane; plasma membrane; cytoplasm; extracellular region; membrane
Genetic constraint (gnomAD): Loss-of-function variants: 109 observed, 152.27 expected, observed/expected ratio (o/e) 0.72, 90% interval 0.61 to 0.84. The synonymous counts are far from expectation, so gnomAD's model fits this gene poorly and the ratio says little. Missense variants: 1,445 observed, 1,784.3 expected, observed/expected ratio (o/e) 0.81, 90% interval 0.77 to 0.85. Synonymous variants: 547 observed, 657.37 expected, observed/expected ratio (o/e) 0.83, 90% interval 0.77 to 0.89.
Homologues: Orthologues: chimpanzee CD163L1 (99% identical), macaque CD163L1 (91% identical), zebrafish si:ch211-161n3.3 (24% identical), zebrafish si:dkey-21h14.8 (23% identical), zebrafish si:dkey-21h14.14 (23% identical), zebrafish si:dkey-21h14.10 (23% identical), zebrafish si:ch211-161n3.4 (23% identical), zebrafish si:dkey-21h14.9 (21% identical), zebrafish si:dkey-21h14.11 (21% identical), zebrafish si:dkey-21h14.12 (19% identical), zebrafish si:dkey-14d8.20 (17% identical), zebrafish si:ch211-161n3.5 (16% identical), and 5 more. Paralogues in human: CD163 (43% identical), DMBT1 (25% identical), SCART1 (24% identical), SSC5D (19% identical), PRSS12 (15% identical), LOXL2 (13% identical), SSC4D (12% identical), LOXL3 (12% identical), LOXL4 (12% identical), CD6 (11% identical), CD5L (9% identical), CD5 (8% identical), and 3 more.
Diseases named in the same sentence as CD163L1 in open-access papers:
CD163L1 is named in the same sentence as 8 diseases in open-access papers, as found by Europe PMC text mining. Sharing a sentence is not in itself a finding about the gene and the disease. The quoted sentences say what the papers report.
breast carcinoma (1 paper, 2024). "In our study, we observed that CD163L1 is downregulated in breast cancer and closely linked to CD8+ T cell dynamics." (PMID 39202452, 2024).
lung adenocarcinoma (1 paper, 2022). A carcinoma that arises from the lung and is characterized by the presence of malignant glandular epithelial cells. "We also investigated whether there was a correlation between SPP1 gene expression and various macrophage markers, such as CD204, Iba-1, CD68, CD163, and CD163L1, in lung adenocarcinoma tissues." (PMID 36139536, 2022).
tumor (7 papers, 2020 to 2025). "Genes such as MARCO, FN1, ACE, and CD163L1 are likely associated with the immunoregulatory functions of M2 macrophages, which typically promote tissue repair, anti-inflammatory responses, and support tumor growth." (PMID 39697346, 2024). "CD163L1+ macrophages were enriched in cancer-adjacent tissues, but declined progressively in primary tumors and metastases, suggesting a potential tumor-suppressive role in this population." (PMID 41246350, 2025). "Cluster M0 highly expressed immunosuppressive and angiogenic phenotype-related markers (SLC40A1, NRP1, and CD36) and promote tumor progression associated with markers (CD163 and CD163L1)." (PMID 35265520, 2022). "Consistent with the scRNA-seq results, FOLR2 expression was also positively correlated with TRM-related genes (CD163, MRC1, CD163L1 and LYVE1) in the whole-tumor transcriptome from the TCGA STAD database." (PMID 39702278, 2024). "Compared with the adjacent tissues, CD163L1 and KLRB1 mRNA are downregulated in tumor tissues." (PMID 39202452, 2024).
cancer (4 papers, 2018 to 2025). A tumor composed of atypical neoplastic, often pleomorphic cells that invade other tissues. "Compared to paired normal tissues, the expression levels of KLRB1 and CD163L1 were reduced in cancer tissues." (PMID 39202452, 2024). "Consistent with previous results, the protein expression level of CD163L1 is also downregulated in cancer tissues." (PMID 39202452, 2024).
infection (2 papers, 2019 to 2020). The state of being infected such as from the introduction of a foreign agent such as serum, vaccine, antigenic substance or organism. "Previously, genetically modified pigs possessing SRCR 5 substitution with domain homologs from human CD163L1 were not permissive for genotype 1 PRRSV infection but susceptible to the infection by genotype 2 viruses." (PMID 33050150, 2020).
CD163L1 also shares sentences with these, for which no sentence is quoted: IgA nephropathy (1 paper); liver failure (1); melanoma (1).